EGR1 (early growth response 1)
Diseases named in the same sentence as EGR1 in open-access papers (continued):
Sharing a sentence is not in itself a finding about the gene and the disease.
tumor (continued). "Simultaneous delivery of functional DNA and Ce6 to the tumor site resulted in deoxyribozymes-mediated inhibition of the transcription factor EGR-1 (early growth response protein 1), along with photogenerated cellular apoptosis." (PMID 37242807, 2023). "Further validation through the cell viability assay confirmed that the upregulation of Egr1 was instrumental in the synergistic anti-tumor activity observed in the composite treatment with doxorubicin." (PMID 38248651, 2023). "In colorectal cancer, KLF12 promotes tumor growth by directly activating early growth response protein (EGR1)." (PMID 37606530, 2023). "Early growth response-1 (EGR-1) is an important upstream transcription factor that regulates cell proliferation and differentiation and plays an essential role in tumor angiogenesis." (PMID 38193080, 2023). "We demonstrated that tumor cell-derived exosomes enriched with miR-184-3p were taken up by macrophages to inhibit JNK signaling pathway by targeting EGR1, thereby inducing M2 polarization of macrophages and synergistically promoting tumor progression." (PMID 37957722, 2023). "Whereas JUN, HSPH1, HSPA8, HSPA6, HSP90AB1, and EGR1 were found to be the DEGs in both Tumor vs. normal and tumor vs. metastasis group." (PMID 37335089, 2023). "The authors illustrated the impact of the EGR1 gene in tumor initiation, cell death, immune response, and its potential role in the tumor microenvironment." (PMID 37958905, 2023). "Analysis of specific human tumor cells and tissues indicates that EGR-1 acts as both a tumor suppressor and a tumor promoter." (PMID 36233659, 2022). "In this regard, interaction involving the WW domains of YAP with other DNA-binding transcription factors like p73, ERBB4, EGR-1, RUNXs have also been reported which results in context-dependent oncogenic or tumor-suppressive outcomes." (PMID 35526072, 2022). "This formation is mediated predominantly by IFNγ-activated T cells, which subsequently induce phosphorylation of the transcription factors signal transducer and activator of transcription 3 (STAT3) and early growth response-1 (EGR-1) in tumor cells." (PMID 36124553, 2022). "Gain- or loss-of-function experiments revealed that the bevacizumab-resistant tumor cell–derived FGFBP1 induced FAPα expression by enhancing the paracrine FGF2/FGFR1/ERK1/-2/EGR1 signaling pathway in HSCs." (PMID 35951441, 2022). "EGR1 has been shown to have significant tumor suppressor properties in many types of cancer and different KLF TFs have been involved in a large number of cancers." (PMID 35331302, 2022). "The qRT-PCR data revealed that EGR-1 is predominantly higher-expressed in tumor-adjacent normal tissues compared to tumor tissues." (PMID 36233659, 2022). "EGR1 (Early Growth Response 1) has long been dysregulated in many cancers and is known to regulate tumor progression, making it an attractive target for cancer therapy." (PMID 36120336, 2022). "Our preliminary data revealed that Egr-1 is an important tumor suppressor which highly corelates with chemosensitivity in ESCC (in pressing)." (PMID 36207572, 2022). "Further, EGR1 is involved in the polarization of M2 macrophages induced by PD-L1, with anti-PD-L1 treatment promoting tumor resistance and metastasis through regulation of angiogenic osteoclastogenic factors." (PMID 35151325, 2022). "The EGR-1 expression was also higher in tumor-adjacent normal tissue than in tumor lesions from the TCGA database." (PMID 36233659, 2022). "Numerous tumor suppressor genes have been identified to be under the transcriptional regulation of EGR1." (PMID 36338037, 2022).
tumor (continued). "In prostate and gastric cancers, EGR1 expression is often overexpressed in the tumor as compared to surrounding tissue." (PMID 36338037, 2022). "Significantly higher EGR-1 expression was noted in tumor-adjacent normal tissue compared with tumor lesions." (PMID 36233659, 2022). "In gliomas and melanocytomas, EGR1 upregulates tumor suppressor gene p21Waf1/Cip1 which ultimately contributes to tumor cell apoptosis." (PMID 36338037, 2022). "The regulation of the transcription of the heparin enzyme is one of the biological roles that EGR1 performs in tumor cells." (PMID 36046377, 2022). "In our clinical study, the qRT-PCR data indicated that EGR-1 was predominantly overexpressed in tumor-adjacent normal tissue parts." (PMID 36233659, 2022). "A previous study analysis of specific human tumor cells and tissues indicated that EGR-1 participates in tumor suppression." (PMID 36233659, 2022). "Both clinical and in vitro findings concluded that EGR-1 plays a crucial role in tumor suppression of ESCC." (PMID 36233659, 2022). "Proangiogenic growth factors such as basic fibroblast growth factor (bFGF) and VEGF-A are EGR-1 target genes that contribute to tumor angiogenesis." (PMID 35205812, 2022). "Early growth response factor 1 (EGR1) is a transcription factor involved in cell proliferation, differentiation, invasion, and apoptosis and is known to act as tumour‐suppressor or promoter, depending on the cell type and the environment." (PMID 36433652, 2022). "Expression of EGR1 is altered in numerous cancers where EGR1 can play paradoxical roles as either a tumor suppressor or oncogene, depending on the type of cancer and other relevant physiological circumstances." (PMID 36338037, 2022). "Suppress proliferation of tumor cells, down-regulate transcription factors NF-kappa B, AP-1 and Egr-1; down-regulate growth factor receptors; and inhibit the activity of c-Jun N-terminal kinase, protein tyrosine kinases and protein serine/threonine kinases." (PMID 36015535, 2022). "EGR1, a transcription factor, plays a dual role in tumor progression by regulating downstream target genes." (PMID 35069903, 2022). "EGR1 is upregulated in tumor samples from patients with extranodal natural killer T-cell lymphoma (ENKTL), which is an aggressive cancer associated with EBV infection." (PMID 36338037, 2022). "In the two ESCC cell line models, the enhanced invasion, migration, and resistance against chemotherapeutic reagents in the EGR-1 gene knockdown group compared to control also indicated the tumor suppressive effect of EGR-1." (PMID 36233659, 2022). "For example, EGR1 functions as a tumor suppressor by monitoring DNA damage, promoting cell apoptosis, and enhancing the anticancer effects of radiotherapy and chemotherapy." (PMID 35883603, 2022). "In contrast, EGR1, a tumor suppressor gene, was predominantly expressed in post-treatment tumors, and its expression was lower in the stroma around the post-treatment tumor." (PMID 36505794, 2022). "Treatment of PDFS cells with RGFP966 and 5’-AZA also significantly increased the mRNA expression of other tumor suppressors, including EGR1, PTEN, STAT1, and immune stimulatory receptor CD40." (PMID 35646715, 2022). "Together with HIFs, early growth response factor 1 (Egr-1), which is a transcription factor activated by hypoxia, plays a major role in the survival of tumor cells under hypoxic conditions." (PMID 35448004, 2022). "The EGR-1 expression was significantly higher in tumor-adjacent normal tissue than in tumor lesions from our tissue bank (5.87 ± 10.22 vs. 3.97 ± 7.58, p = 0.0015)." (PMID 36233659, 2022).
tumor (continued). "Nevertheless, EGR1, a member of a zinc finger transcription factor family, has been described as tumor suppressor in cancer progression." (PMID 33579362, 2021). "Thereafter, the RT-qPCR results suggested that the expression of EGR1 was elevated in the clinical tumor tissues versus that in the para-cancerous tissues." (PMID 34409922, 2021). "stEMF further upregulated the pro-inflammatory cytokine interleukin 18 (IL18) alongside early growth response 1 (EGR1), an important transcription factor with multifaceted roles in tumor formation and proliferation as well as inflammation." (PMID 34574442, 2021). "The results indicated that EGR1 has a tumor repressive effect in cell malignant transformation and lung tumorigenesis upon B[a]P/BPDE treatment." (PMID 34497759, 2021). "In primary tumor tissues, weak and mostly cytoplasmic staining for EGR1 was observed in the tumor cells." (PMID 34439267, 2021). "In some cases, EGR1 is a tumor suppressor that helps to monitor DNA damage, promotes tumor cell apoptosis, and enhances the anticancer effects of radiotherapy and chemotherapy." (PMID 33842351, 2021). "By contrast, in certain tumor microenvironments, such as hypoxic ones, EGR1 expression increases to maintain tumor cell survival, proliferation, and metastasis and tumor angiogenesis." (PMID 33842351, 2021). "Antagonized miR-377-3p reversed the effect of EGR1 in cell malignant transformation, thus supporting the critical role of miR-377-3p in regulating EGR1 expression to promote cell transformation and tumor formation." (PMID 34497759, 2021). "Previous studies showed that EGR1 regulates the transactivation of genes involved in tumor growth inhibition as an anticancer gene in cancer, and that EGR1 inhibits proliferation, migration and invasion." (PMID 34681812, 2021). "It was found that the positive staining of the proliferation marker Ki-67 in tumor tissues was reduced after EGR1 suppression." (PMID 34409922, 2021). "To investigate the role of EGR1 in Scutellarin‐induced tumour suppression, we first used siRNA to knock down EGR1 in 143B and U2OS cells." (PMID 34346162, 2021). "A significant decrease in tumor weights was observed in the experimental group compared to the control, and an increase in Egr1 expression was noticed along with a decrease in cyclinB1 and CDC25c expression." (PMID 34638282, 2021). "As a downstream protein of the MAPK signaling pathway, EGR1 can promote transcriptional activation of cyclin D1 in many tumor types and maintain the mitosis of tumor cells." (PMID 33842351, 2021). "EGR1 is a direct regulator of many tumor suppressor genes, also SP TF family members (SP1 and SP2) are involved in gene regulation in tumors." (PMID 34282050, 2021). "We found that the expression of EGR1 was significantly higher in normal samples than in tumor samples in the THCA cohort." (PMID 33477921, 2021). "Lastly, further studies are needed on the mechanism of EGR1 regulation of T cell state to contribute to tumor cell immune evasion." (PMID 33990633, 2021). "MiR-377-3p antagomir reversed the effect of EGR1 downregulation in cell malignant transformation and tumor initiation models." (PMID 34497759, 2021). "Next, we analyzed the HNC profiles using Oncomine platform as well as the HNC profiles available in the GEO database and observed the upregulation of (Early Growth Response1) EGR1 in HNC tumor tissues as compared to normal tissue." (PMID 34616729, 2021). "Increased nuclear translocation of EGR1 was found to enhance the transcription activity of miR-3928 v and downregulated expression of voltage-dependent anion channel 3, a tumor-suppressor, thereby increasing malignancy of LC cells." (PMID 34409922, 2021).
tumor (continued). "In head and neck squamous cell carcinoma, oxytocin is thought to inhibit tumor invasion and metastasis by upregulating EGR1 through an EGFR-and-ERK–dependent pathway." (PMID 33842351, 2021). "EGR1 exhibits either oncogenic or tumor-suppressive properties depending on the types of cells and stimuli." (PMID 33477921, 2021). "EGR1 acts as an anti-oncogene engaging in multiple cancer processes, including cancer cell proliferation, apoptosis, and migration and even affects tumor microenvironment." (PMID 34178038, 2021). "The level of GPX4 was reduced, and EGR1 was increased in tumor for 13-treated group compared with vehicle group." (PMID 33472669, 2021). "EGR1 contributes to tumor invasion and metastasis mainly by starting the expression of E-cadherin transcriptional inhibitors (SNAIL and SLUG)." (PMID 33842351, 2021). "Our findings supported the induction of EGR1 as a stress-related and tumor defensive mechanism also mediating pro-survival/pro-metastatic signals." (PMID 34857011, 2021). "ATF3, a highly conserved transcription factor, was described as a principal target of EGR1 and discussed as a tumor suppressor and promoter." (PMID 34497759, 2021). "A constitutive ERK pathway activation has been correlated to high EGR1 expression in several tumor cells." (PMID 34857011, 2021). "EGR1 overexpression significantly suppressed cell viability compared with the control, indicating that EGR1 acts as a tumor suppressor in THCA cells." (PMID 33477921, 2021). "In other words, SNAIL and SLUG can inhibit the expression of E-cadherin, and EGR1 plays an important role in tumor EMT by regulating SNAIL and SLUG." (PMID 33842351, 2021). "EGR1, a zinc finger transcription factor, plays an important role in controlling inflammation, growth, differentiation, apoptosis and tumor progression." (PMID 34615546, 2021). "Several genes of antiviral immune response pathways such as HLA-B, HLA-C, HLA-DQB1 IFI6, IFITM3, CD74, and tumor suppressor genes EFEMP1 and EGR1, are upregulated in tumor and downregulated in TAS." (PMID 34316327, 2021). "EGR1 overexpression not only promotes tumor growth but also launches the p38 MAPK signaling pathway." (PMID 33842351, 2021). "EGR1 has been increasingly attracting research attention due to its tumor-suppressing role in the occurrence and development of tumors." (PMID 34497759, 2021). "EGR1 is involved in the cell cycle progression of various tumor types, and also in hepatic regeneration in mammals." (PMID 33578707, 2021). "Our findings establish that EGR1 as a potential tumor suppressor that leads to NTPAM-induced apoptotic cell death via GADD45α regulation in THCA cells." (PMID 33477921, 2021). "EGR-1 has been identified as a tumor suppressor as its levels are reduced in several tumor models, including AML." (PMID 32260549, 2020). "The upregulation of EGR-1 promotes differentiation in the myeloid lineage, but its tumor suppressive function depends on the nature of the transforming oncogene." (PMID 32260549, 2020). "In CRC, EGR1 has been found to promote or suppress tumor growth, depending on the cell type and environment." (PMID 33346749, 2020). "EGR1 is a stress response transcription factor with multiple tumor suppressor roles in breast tissue." (PMID 32391121, 2020). "In in vivo studies, the NOD/SCID mice model was established to explore the effects of Hep3B and Hep3B/So cells with inhibited SNHG16 or miR‐23b‐3p on tumor size, EGR1 expression, and autophagy." (PMID 32324343, 2020). "The mean fraction of EGR1 + tumour cells significantly declined from central tumour to periphery (5.3% vs. 1.6%, P < 0.05)." (PMID 32518380, 2020).
tumor (continued). "EGR1, a tumor suppressor, which down-regulated in ESCC tissues is involved in tumorigenesis and results in enhancive tumor transformation." (PMID 32662828, 2020). "Several other tumor suppressors are also targets of EGR1, including transforming growth factor-β, phosphatase and tensin homolog, p73 and fibronectin." (PMID 33346749, 2020). "Our previous study showed that in NHSCC cells, oxytocin, which sustained EGR1 expression, preferentially inhibits tumor cell invasion in an EGFR-dependent manner." (PMID 30845713, 2019). "Curcumin has the ability to suppress tumor cell proliferation and downregulate transcription factors Nf-κB, AP-1, and Egr-1." (PMID 31052496, 2019). "The results showed that knocking down SAP18 in CXCR2−/− tumor-bearing mice increased the percentage of mo-MDSCs, and the level of Pu.1 and Egr1 mRNA was also recovered." (PMID 31395859, 2019). "EGR1 expression is low in many tumor types, such as breast, lung, glioblastoma, astrocytoma, and fibrosarcoma tumors." (PMID 30925677, 2019). "The alterations of EGR1 expression were also observed when tumor cells were treated by different gradient cobalt chloride for 24 h." (PMID 31068761, 2019). "Further, sustained EGR1 expression can result in the inhibition of tumor cell invasion and tumor growth in in vitro and in vivo analysis." (PMID 30845713, 2019). "Egr-1, an AP-1 subunit with tumor-suppressive activity, was also elevated by R-propranolol treatment." (PMID 31701018, 2019). "EGR1 is an early-phase reactive molecule in response to various stimuli that plays a significant role in hypoxia-induced tumor progression, survival and angiogenesis." (PMID 31068761, 2019). "EGR1 is induced by a variety of stimuli, including hypoxia, ionizing radiation, hyperglycemia and chemotherapy drugs, and it promotes or inhibits tumor proliferation." (PMID 31068761, 2019). "Induction of SRF by chemerin activated its target gene early growth response-1 (EGR1), a transcription factor, which has been suggested to be a tumor suppressor due to its growth inhibitory and pro-apoptotic effects." (PMID 31370263, 2019). "And the important transcription factors for the differentiation of monocytes (e.g., Pu.1 and Egr1) were expressed at low levels in CXCR2−/− tumor-bearing mice." (PMID 31395859, 2019). "Analysis of certain human tumor cells and tissues indicate that Egr1 exhibits a prominent tumor suppressor function." (PMID 30845713, 2019). "The qRT‐PCR was performed to detect the expression of EGR1, and the results showed that the expression of EGR1 mRNA levels was higher in GC tissues compared with their respective non‐tumour tissue." (PMID 31515938, 2019). "As a member of the zinc finger transcription factor family, EGR1 has been widely reported to serve as a tumor suppressor gene in various tumors." (PMID 31752873, 2019). "Egr-1 is induced by hypoxia and plays a critical role in hypoxia-induced tumor progression, survival, and angiogenesis." (PMID 29636841, 2018). "We and other groups showed the involvement of Egr-1 for hepatic fibrosis, hepatocarcinogenesis, tumor malignancy, and chemo resistance." (PMID 29360739, 2018). "It will an important future direction of this work to determine if reactivation of EGR1 in tumor cells can sensitize tumors to chemotherapy in vivo." (PMID 29719592, 2018). "As FAP expression was associated with EGR1 upregulation, we assessed the presence of nuclear EGR1 in TAMs in 4T1 tumours grown in WT and Il6−/− mice and found a significant reduction of nuclear EGR1 in the TAMs of Il6−/− mice." (PMID 30054470, 2018).